OGFR (opioid growth factor receptor)
Description:
Receptor for opioid growth factor (OGF), also known as Met-enkephalin. Seems to be involved in growth regulation.
Synonyms: 7-60
Tractability: PROTAC: ubiquitination databases record sites on it; its protein half-life has been measured.
Gene: Protein-coding gene on chromosome 20 (62,804,178 to 62,814,000, forward strand). Ensembl gene ENSG00000060491.
Subcellular location: Cytoplasm; Nucleus
Subcellular location (Human Protein Atlas): Nucleoplasm
Gene Ontology:
Molecular function: protein binding; opioid growth factor receptor activity; signaling receptor activity
Biological process: regulation of cell growth
Cellular component: cytoplasm; membrane; nucleus
Genetic constraint (gnomAD): Loss-of-function variants: 19 observed, 28.33 expected, observed/expected ratio (o/e) 0.67, 90% interval 0.47 to 0.98. The upper end of that interval is the gene's LOEUF score, 0.98, which puts it in group 4 of 6, group 1 being the genes least tolerant of losing a copy. Missense variants: 864 observed, 838.6 expected, observed/expected ratio (o/e) 1.03, 90% interval 0.97 to 1.09. Synonymous variants: 364 observed, 335.96 expected, observed/expected ratio (o/e) 1.08, 90% interval 0.99 to 1.18.
Homologues: Orthologues: chimpanzee OGFR (88% identical), macaque OGFR (83% identical), guinea pig OGFR (51% identical), rat Ogfr (50% identical), mouse Ogfr (49% identical), dog OGFR (44% identical), zebrafish ogfr (25% identical), tropical clawed frog ogfr (19% identical), zebrafish ogfr1 (19% identical), zebrafish ogfr2 (18% identical). Paralogues in human: OGFRL1 (22% identical).
Diseases named in the same sentence as OGFR in open-access papers:
OGFR is named in the same sentence as 36 diseases in open-access papers, as found by Europe PMC text mining. Sharing a sentence is not in itself a finding about the gene and the disease. The quoted sentences say what the papers report.
diabetes (8 papers, 2011 to 2024). "Depending on the duration of OGFr blockade, opioid antagonists, such as naloxone, are effective therapies for cancer, autoimmune diseases and complications associated with diabetes." (PMID 36836125, 2023). "Preclinical studies have reported that the opioid growth factor (OGF) – OGF receptor (OGFr) regulatory pathway has a role in reversing or ameliorating several ocular-related complications of diabetes." (PMID 30691415, 2019). "Sustained blockade of the interactions between OGF and OGFr results in accelerated cell replication, and thus enhances corneal repair, restores corneal surface sensitivity, and reverses dry eye in animal models of diabetes." (PMID 30691415, 2019). "In these studies, serum or tissue levels of OGF or OGFr were not determined, and because of IACUC limitations on maintaining animals with uncontrolled T1D, peptide and receptor expression levels in early and late stages of diabetes have not been systematically reported." (PMID 32368758, 2020).
lung carcinoma (8 papers, 2018 to 2025). "For instance, OGFR has been linked to decreased cell proliferation in lung carcinoma and breast cancer, and indeed, we did find that OGFR was overexpressed in our cancer samples." (PMID 35463331, 2022). "MET promotes apoptosis in lung cancer cells and increases the expression of the opioid growth factor receptor, but these effects disappear when the receptor is blocked." (PMID 37509632, 2023). "MET increased the expression of the opioid growth factor receptor and, by activating the caspase 3/Bax/Bcl-1 signaling pathway, promoted apoptosis in lung cancer cells." (PMID 37509632, 2023). "Morphine, via the opioid growth factor receptor, suppressed lung cancer cell proliferation (H1975); this suppression occurred in the cell cycle S phase." (PMID 37509632, 2023). "The expression of the OGFR in lung cancer tissues is significantly higher than in para-carcinoma tissues, and morphine plays a role in the OGFR and inhibits cell proliferation." (PMID 35966857, 2022). "Another data also supported the fact that morphine could affect the opioid growth factor receptor (OGFR) and finally inhibit proliferation of lung cancer cells." (PMID 35966857, 2022). "Moreover, binding of morphine to the opioid growth factor receptor (OGFR), a negative regulator of normal and cancer cell proliferation, resulted in lung cancer growth suppression." (PMID 35565382, 2022). "Lung cancer tissues and cell lines expressing OGFR which interacts with morphine may restrain lung cancer progression." (PMID 33968773, 2021). "Moreover, it has been demonstrated that opioid growth factor receptor (OGFR), a negative regulator of cell proliferation is involved in subsequent morphine-induced lung cancer growth inhibition." (PMID 33968773, 2021). "In addition, MCF7 cells express the opioid-growth factor receptor (OGFr), which contributes to morphine-induced suppression of lung cancer cell proliferation." (PMID 29571287, 2018). "Probable activation of other opioid receptors by MENK, in the absence of OGFR in A549 cells resulting in increased invasiveness, supports data presented in another report on the same lung cancer A549 cell line." (PMID 39861181, 2025).
pancreatic cancer (6 papers, 2008 to 2024). "Cannabinoid receptor 2 and opioid growth factor receptor are highly expressed in pancreatic cancer tissue and their high expression improves OS, whereas high delta opioid receptor expression reduces OS." (PMID 37627066, 2023). "For example, the MET/opioid growth factor receptor system augmented the cyclin-dependent kinase inhibitor p21 protein expression, decreasing the progression of human pancreatic cancer." (PMID 37509632, 2023). "First, OGF and OGFr have been identified in human pancreatic cancer cell lines and tumor tissues by immunohistochemistry." (PMID 18190706, 2008). "Gene expression, and protein expression of OGFr, as well as binding activity have been identified and characterized in pancreatic cancer cell lines revealing the autocrine nature of this growth regulatory axis." (PMID 18190706, 2008). "OGF is a constitutively expressed native opioid that is autocrine produced and secreted, and interacts with the OGF receptor (OGFr) to inhibit the growth of pancreatic cancer cells in vitro and in tumor xenografts." (PMID 18190706, 2008). "Moreover, MET, through the opioid growth factor receptor, exerts an antitumoral effect against colon cancer, neuroblastoma, ovarian cancer, head and neck squamous cell carcinoma, and pancreatic cancer." (PMID 37509632, 2023). "The opioid growth factor (OGF) and its receptor, OGFr, regulate proliferation in normal and cancer cells, and their expression has been shown to be downregulated in ovarian cancer and to restrict proliferation in pancreatic cancer." (PMID 36361532, 2022). "Second, OGFr has been characterized in human pancreatic cancer cells and surgical specimens by receptor binding, and shown to have at least a 10-fold greater affinity for OGFr than any other natural or synthetic opioid peptide (including those specific for μ, δ, or κ classical opioid receptors)." (PMID 18190706, 2008). "However, the expression of OGFr in pancreatic cancer cells is higher than in normal cells." (PMID 38399336, 2024). "Using OGFr knockdown experiments, the present report now shows, for the first time, that the specific and singular receptor for OGF action on the replication of a human pancreatic cancer cell line is OGFr." (PMID 18190706, 2008).
ovarian carcinoma (4 papers, 2022 to 2023). A malignant neoplasm originating from the surface ovarian epithelium. "Enkephalin has been reported in tumor cells in ovarian carcinoids and MET and the opioid growth factor receptor in human ovarian cancer cells." (PMID 37509632, 2023). "Upregulation of opioid growth factor signaling through OGFR (opioid growth factor receptor) suppresses proliferation in several other malignancies, including lung and ovarian cancer." (PMID 35892849, 2022). "The opioid growth factor (OGF) and the OGFR axis have decreased abundance in ovarian cancer." (PMID 36214631, 2022).
squamous cell carcinoma of the head and neck (3 papers, 2018 to 2023). "Downregulation of the opioid growth factor receptor favored the progression of head and neck squamous cell carcinoma, and LEU has been detected in head and neck paragangliomas." (PMID 37509632, 2023). "Downregulation of the opioid growth factor receptor favored the progression of head and neck squamous cell carcinoma." (PMID 37509632, 2023). "Zagon and McLaughlin32,33 documented the presence of the opioid growth factor receptor(OGFr) axis in a number of human cancers including neuroblastoma, pancreatic, colon,breast, renal, squamous cell carcinoma of the head and neck, and hepatocellularadenoma." (PMID 29258346, 2018).
Hyperglycemia (2 papers, 2022 to 2023). An increased concentration of glucose in the blood. "At 4 and/or 8 weeks of hyperglycemia, different cohorts of animals were euthanized, eyes removed and processed for assessment of limbal morphology, expression of OGF, OGFr, cytokeratin 15, a marker for limbal cells, and Ki-67, a marker of proliferation." (PMID 37304310, 2023).
alcohol addiction (1 paper, 2022). "Furthermore, Naltrexone (NTX), a commonly accepted treatment for drug and alcohol addiction as well as a potent antagonist of OGFR 13, 15, 24, successfully rescued the increase in apoptosis induced by CIRBP knockdown." (PMID 35541895, 2022).
cervical cancer (1 paper, 2021). A primary or metastatic malignant neoplasm involving the cervix. "Naltrexone has a strong blocking effect on OGFr, and we detected the expression of OGFr when cervical cancer cells treated with LDN." (PMID 33540155, 2021). "In the present study, we found that OGFr was low expressed in tumors of patients with cervical cancer." (PMID 33540155, 2021). "We found that OGFr was significantly downregulated in cervical cancer tissues." (PMID 33540155, 2021). "We found that OGFr was low expressed in cervical cancer tissues." (PMID 33540155, 2021). "In this study, we found that OGFr was low expressed in tumors of patients with cervical cancer." (PMID 33540155, 2021). "Furthermore, we also checked the expression of OGFr in mRNA level of tissues, quantitative PCR (qPCR) was performed in 60 specimens: 30 specimens of cervical cancer tissues and 30 of paired adjacent non-cancerous tissues." (PMID 33540155, 2021).
colorectal cancer (1 paper, 2022). A primary or metastatic malignant neoplasm that affects the colon or rectum. "To conclude, in patients with stage II and III colorectal cancer, overall expression of MOR and OGFR was significantly increased but was not different between previously matched patients with or without recurrence." (PMID 35463331, 2022). "In patients with stage II and III colorectal cancer, overall expression of MOR and OGFR was significantly increased but was not different between previously matched patients with or without recurrence." (PMID 35463331, 2022).
gastric cancer (1 paper, 2021). A primary or metastatic malignant neoplasm involving the stomach. "Co-citation cluster labels revealed characteristics of ten main clusters: total intravenous anesthesia, opioid growth factor receptor, gastric cancer cell, opioid receptor, murine model, natural killer cell activity, health-related quality, glioma cell, opioid switching and mu-type opioid receptor." (PMID 34458138, 2021).
gastric tumor (1 paper, 2025). "Methionine enkephalin (MENK), an endogenous opioid pentapeptide originating from proenkephalin A, has demonstrated the ability to elevate opioid growth factor receptor (OGFr) expression and inhibit PI3K/AKT/mTOR signaling in both TAMs and gastric tumor cells." (PMID 41459539, 2025).
hepatocellular carcinoma (1 paper, 2023). A malignant tumor that arises from hepatocytes. "MET blocked the proliferation of hepatocellular carcinoma cells, and silencing the opioid growth factor receptor favored their proliferation." (PMID 37509632, 2023).
leishmaniasis (1 paper, 2019). Infectious disease that is transmitted through the bite of hematophagous female phlebotomine sand flies. "The morphine effects on imiquimod as an opioid growth factor receptor (OGFr) stimulant or on nalmefene as a blocker of opioid receptor have not previously been studied in leishmaniasis." (PMID 31673257, 2019).
liver cancer (1 paper, 2021). An epithelial or non-epithelial malignant neoplasm that arises from the liver. "Our results also showed up-regulation of the OGFR in liver cancer cells pre-exposed to morphine indicating that similar mechanism may take part in different cell lines." (PMID 33968773, 2021). "Our results showed that morphine could suppress malignant behavior of liver cancer cells by up-regulation of the OGFR and down-regulation of MOR, uPA and MMP-9." (PMID 33968773, 2021). "We detected the protein and mRNA level of OGFR, MOR, uPA and MMP-9 in Hep3B/HepG2 cells to explore the molecular mechanisms through which morphine could affect the liver cancer cells." (PMID 33968773, 2021).
oropharyngeal carcinoma (1 paper, 2025). Carcinoma, predominantly squamous cell, arising from the epithelial cells of the oropharynx. "We analyzed the effects of low-dose NTX on growth, response to chemotherapy, and OGFr expression in oropharyngeal carcinoma cell lines." (PMID 41226687, 2025).
renal carcinoma (1 paper, 2024). A carcinoma arising from the epithelium of the renal parenchyma or the renal pelvis. "TLR4, OPRL1, and OGFR opioid receptor genes have been reported to be associated with renal cancer progression." (PMID 38352696, 2024).
cancer (24 papers, 2008 to 2025). A tumor composed of atypical neoplastic, often pleomorphic cells that invade other tissues. "Low-dose naltrexone (LDN) exhibits antagonistic action against the opioid growth factor receptor (OGFr), whose signaling is associated with the survival, proliferation, and invasion of cancer cells." (PMID 38539570, 2024). "Somatic mutations of OGFR identified in human cancers have been shown to disrupt nuclear trafficking of the receptor and attenuate the growth-suppressive response to OGF, indicating that alterations in OGFR structure directly influence cancer cell proliferation and therapeutic sensitivity." (PMID 41463187, 2025). "Because our results indicated that high CB2 and OGFR tumor tissue gene expression improved OS, we hypothesize that piritramide’s negative effects may be linked to interactions with specific receptors in cancer and immune system cells." (PMID 37627066, 2023). "The common feature of these cancers is primarily the increased expression of OGFr, and the therapeutic effects of LDN are mainly due to its transient properties, inhibiting this receptor." (PMID 38539570, 2024). "The consequences of the transient inhibition of the OGF–OGFr axis translate into positive effects in inhibiting the growth, proliferation, and survival of cancer cells, especially in epithelial-origin tumors characterized by increased OGFr expression." (PMID 38539570, 2024). "The assessment of the impact of low-dose MNTX on the in vitro culture of human non-small cell lung cancer cells showed that the transient blockade of the OGFr by the treatment led to the inhibition of the growth and proliferation of cancer cells." (PMID 38539570, 2024). "OGF, an endogenous peptide interacting with the OGF receptor (OGFr), plays a crucial role in inhibiting cell proliferation across various cancer types." (PMID 38399336, 2024). "Our results showed that cancer-specific survival was increased by postoperative analgesia with morphine, cannabinoid receptor 2, and opioid growth factor receptor cancer tissue gene expressions but was reduced by delta opioid receptor gene expressions." (PMID 37627066, 2023). "Beyond ROS, our study of CIRBP-mediated OGFR regulation undoubtedly provides an alternative explanation for cardiotoxicity induced by cancer therapy." (PMID 35541895, 2022). "Restoration of CIRBP and/or blunting OGF/OGFR signal are potential treatments for cardiotoxicity acquired from cancer therapies." (PMID 35541895, 2022). "Data from previous studies suggest that OGF/OGFR signaling inhibits cell proliferation and survival during development, cancer, wound healing and angiogenesis." (PMID 35541895, 2022). "The cytotoxic effect of imiquimod against various cancers has been investigated, and it was shown that it induces apoptosis as well as increasing levels of the opioid growth factor receptor (OGFr)." (PMID 32850486, 2020). "An increase in OGF-OGFr activity in cancer cells by i) addition of exogenous OGF, ii) treatment with imidazoquinoline compounds such as imiquimod and resiquimod, or iii) transfection of sense cDNA for OGFr, depresses cell proliferation." (PMID 19835629, 2009). "These updated findings suggest that OGFR exerts context-dependent regulatory effects that extend beyond simple G0/G1 checkpoint control, supporting a more complex model in which OGFR integrates multiple signaling cues relevant to cancer biology." (PMID 41463187, 2025). "Among these changes, the splicing improvements and upregulation of OGFR protein levels may be particularly noteworthy in the context of snaR-A and cancer, given that OGFR is a well-established inhibitor of cell proliferation and tumorigenesis." (PMID 41290606, 2025). "An increase in OGFr expression in cancer cells was observed." (PMID 38539570, 2024). "Morphine analgesia, CB2, and OGFR cancer tissue gene expression thus improved CSS resp." (PMID 37627066, 2023).
cancer (continued). "An extensive literature shows that OGF interacts with OGFr to regulate cell the proliferation of human and animal cells, normal and cancer, implying that the effect on control of cell number by endogenous OGF, as well as exogenously administered peptide, is mediated by this receptor." (PMID 19835629, 2009). "The study showed that low-dose MNTX, by transiently blocking OGFr, inhibited the OGF-induced suppression of cancer cell growth, thereby significantly improving survival and treatment outcomes in the studied animals." (PMID 38539570, 2024). "Moreover, LDN increased the expression of OGF and OGFr, proving that LDN stimulates the endogenous opioid system, which inhibits the proliferation of cancer cells." (PMID 38539570, 2024). "Lastly, we included the OGFr in our search for evidence of ORs expression in cancer even though it is not a classical opioid receptor." (PMID 35004315, 2021). "This confirmed that it was the duration of the OGFr blockade, and not thedosage of the naltrexone, that blocked accelerated cancer cell growth." (PMID 29258346, 2018). "Evidence describing the immunomodulating effects of LDN and its impact on the synthesis and modulation of signaling pathways associated with IL-2 supports the hypothesis that IL-2+LDN immunotherapy may provide therapeutic benefits in cancers showing increased expression of OGF and OGFr." (PMID 38539570, 2024). "Furthermore, R-848 also had a direct effect on tumor cells - it upregulates the expression of opioid growth factor receptor, which leads to the anti-proliferative and cancer suppressive effects, independent of immune function." (PMID 27927165, 2016).